CTLA4 (cytotoxic T-lymphocyte associated protein 4)
Diseases named in the same sentence as CTLA4 in open-access papers (continued):
Sharing a sentence is not in itself a finding about the gene and the disease.
melanoma (continued). "We evaluated genetic signatures to predict toxicity and tumor response to anti-CTLA-4 treatment alone in melanoma patients using three separate cohorts." (PMID 40721801, 2025). "Combining SRS with ICIs has been clinically associated with improved local control and mOS in NSCLC patients with BM, and enhanced intracranial control has been observed in melanoma BM treated with CTLA-4 inhibitors plus SRS." (PMID 41008908, 2025). "We noticed that in melanoma and lung cancer cells, blocking the lysosomal degradation pathway with ConcA only partially rescued constitutive CTLA4 degradation." (PMID 39404738, 2025). "Ipilimumab, an anti-CTLA-4 antibody, has demonstrated significant efficacy in melanoma; however, its clinical benefit in osteosarcoma remains uncertain." (PMID 40170852, 2025). "Immune checkpoint inhibitors (ICI) redefined the treatment of advanced melanoma in 2011 with the approval of ipilimumab, a CTLA-4 inhibitor, following the results of MDX010–20 showing significant improvement in survival with acceptable toxicity." (PMID 41179680, 2025). "Immune checkpoint (ICP) inhibitors targeting CTLA‐4, PD‐1, and PD‐L1 have shown significant clinical efficacy in treating various cancers, including lung cancer, melanoma, and bladder cancer." (PMID 41198144, 2025). "This phase 1b clinical trial was conducted in patients with advanced melanoma who were eligible for SOC immunotherapy with a PD-1 inhibitor alone or in combination with a CTLA-4 inhibitor." (PMID 41049010, 2025). "Immune checkpoint inhibitors (ICIs), including anti-CTLA-4 and anti-PD-1/PD-L1 therapies, have revolutionized melanoma treatment, yet resistance remains common due to TME immunosuppression." (PMID 40936894, 2025). "In efforts to enhance therapeutic outcomes, a phase II study evaluated the combination of T-VEC with ipilimumab, a CTLA-4 checkpoint inhibitor, in unresectable melanoma." (PMID 40508177, 2025). "ICIs, antibodies that target the cytotoxic T-lymphocyte-associated protein 4 (anti-CTLA-4) and programmed cell death protein 1 (antiPD-1), are used to treat unresectable melanoma, resulting in a dramatic improvement in survival of patients." (PMID 40652057, 2025). "This phenomenon has been observed in NSCLC patients treated with pembrolizumab (an anti-PD-1 antibody), as well as in melanoma patients who showed favorable clinical responses to ipilimumab (an anti-CTLA-4 antibody)." (PMID 41584608, 2025). "Recently, a dog with anti-PD-L1-resistant melanoma exhibited a complete remission of an oral neoplastic lesion following anti-CTLA4 therapy." (PMID 41488614, 2025). "Anti-CTLA-4 agents in melanoma significantly improved disease control (OR: 1.55; 95% CI: 1.37–1.77; p < 0.0001)." (PMID 41301042, 2025). "In particular, immune checkpoint inhibitors targeting PD-1/PD-L1 and CTLA-4 have significantly improved clinical outcomes in patients with melanoma, non-small cell lung cancer, and renal cell carcinoma." (PMID 40108668, 2025). "Immune checkpoint inhibitors, particularly anti-PD-1 and anti-CTLA-4 agents, have become the cornerstone of treatment in advanced melanoma." (PMID 41301010, 2025). "Immune checkpoint inhibitor (ICI) treatment blocking PD-1, PD-L1, PD-L2, and CTLA4 has been demonstrated to be an effective treatment for various cancers including melanoma." (PMID 40864319, 2025). "Subsequently, overall survival (OS) analysis indeed confirmed that cases exhibiting high PAN3-AS1 levels had poor survival rates when they received PD1 and CTLA4 antibody treatment in melanoma." (PMID 41502505, 2025). "Experience from melanoma brain metastases shows that combining BRAF/MEK inhibitors with PD-1/CTLA-4 checkpoint inhibitors improves intracranial tumor control, and some authors have extrapolated this approach to primary meningeal melanoma." (PMID 41294657, 2025).
melanoma (continued). "At present, immunotherapy for patients with melanoma has immunocheckpoint inhibitors, including CTLA-4 inhibitors and PD-1/PD-L1 inhibitors, which is one of the main immunotherapies used to treat melanoma." (PMID 40527765, 2025). "Ipilimumab is a fully human IgG1 monoclonal antibody and was the first CTLA-4 inhibitor to demonstrate significant survival benefits in advanced melanoma." (PMID 40075753, 2025). "In a retrospective study from MD Anderson, 55 patients with advanced KIT-mutant melanoma were treated with anti-CTLA-4 and/or anti-PD-1 therapy." (PMID 41301010, 2025). "We conducted a mixed‐methods study of 38 male patients aged 18–39 with metastatic or locally advanced melanoma treated with first‐line PD‐1/PD‐L1/CTLA‐4 therapies at a single academic center between 2013 and 2024." (PMID 41317093, 2025). "In the past decade, the U.S. FDA approval of PD-1 and CTLA-4 inhibitors has revolutionized treatment of advanced melanoma." (PMID 40351833, 2025). "Overall, nivolumab (anti-PD-1), pembrolizumab (anti-PD-1), and ipilimumab (anti-CTLA-4) have shown sustained tumor regression, decreased recurrence rates, and prolonged overall survival in melanoma." (PMID 40872475, 2025). "Ipilimumab, an anti-CTLA-4 monoclonal antibody approved for use in melanoma, has been shown to prolong survival." (PMID 40872475, 2025). "Targeted therapies suppress key pathways like RAS–RAF–MEK–ERK, and immune checkpoint inhibitors against PD‐1 and CTLA‐4 have shown efficacy in treating advanced melanoma but also other cancers." (PMID 41078003, 2025). "Patients treated with first-line anti-PD1 ± anti-CTLA4 for advanced melanoma were retrospectively identified from 11 melanoma centers in The Netherlands." (PMID 39980388, 2025). "Melanoma patients who respond to anti-CTLA-4 or anti-PD-1 therapy are also characterized by increased immunoproteasome expression associated with increased cytotoxic immune cell infiltration and upregulation of the IFN-γ pathway." (PMID 40108693, 2025). "Ipilimumab, a CTLA-4 inhibitor, lowers the T cell activation threshold and expands melanoma-reactive CD8+ T cell populations, while selectively depleting tumor-infiltrating Tregs via antibody-dependent cellular cytotoxicity (ADCC)." (PMID 40666508, 2025). "Cohort 2 consisted of 5,705 patients with ≥1 prescriptions for anti-PD-1 and anti-CTLA-4 medications following an ICD-10-CM encounter diagnosis of melanoma." (PMID 40351833, 2025). "The first-in-class anti-CTLA-4 (aCTLA-4) mAb, ipilimumab, demonstrated durable clinical benefits in melanoma, marking a paradigm shift in oncology and earning FDA approval in 2011." (PMID 40075753, 2025). "Concerning CTLA-4, it should be noticed that despite its prevalence in the T cell lineage, its expression in melanoma has been demonstrated." (PMID 39837817, 2025). "In several cancers, including melanoma, head and neck, and prostate tumors, EZH2 inhibition is associated with increased tumor immunogenicity and enhanced responsiveness to CTLA-4 or PD-1/PD-L1 blockade." (PMID 41463268, 2025). "More than ten years have passed since anti-PD-1 and anti-CTLA-4 antibodies were first introduced as treatments for unresectable melanoma, marking a significant shift in therapeutic approaches." (PMID 40647561, 2025). "For example, in mouse melanoma models, combing CTLA‐4 blockade with cytokines such as GM‐CSF or antibodies targeting co‐stimulatory receptors like CD40 synergistically enhances tumour rejection." (PMID 40415479, 2025). "An increase in soluble forms of MICA/B (sMICA/B) has been detected in serum from melanoma patients, which correlates with poor survival in response to ipilimumab (anti-CTLA-4 mAb) treatment." (PMID 39837817, 2025). "In contrast, two other studies—one on melanoma (anti-PD-1 ± anti-CTLA-4) and one on gastrointestinal tract tumors (anti-PD-1)—reported MCP-1 as an unfavorable prognostic marker." (PMID 39982537, 2025).
melanoma (continued). "Thirty-six (69.2%) had melanoma, and most were undergoing treatment with a PD-1 inhibitor alone (n = 33, 63.5%) or in combination with a CTLA-4 inhibitor (n = 10, 19.2%)." (PMID 40354015, 2025). "This is not unprecedented; a study has found that MAGE-A3/6 expression predicts the resistance to CTLA-4 blockade therapy in melanoma patients." (PMID 40141091, 2025). "Melanoma is highly immunogenic, and the introduction of anti-CTLA-4 and anti-PD-1 therapies has significantly enhanced treatment outcomes for advanced or metastatic cases." (PMID 40061141, 2025). "PD-1 and CTLA-4 inhibitors in combination therapy have shown significant clinical efficacy in treating advanced melanoma compared to monotherapies." (PMID 40004731, 2025). "RNA-seq data reveal that while the membrane-bound form of CTLA-4 is more abundant in lung adenocarcinoma and melanoma, sCTLA-4 is correlated with immune suppression." (PMID 40739089, 2025). "The RNA-seq data for Melanoma treated with anti-CTLA-4 therapy shows that the expression level of GSDMD significantly decreased after treatment (log2FC = -1.1007), with a p-value of 0.021." (PMID 40491921, 2025). "Preliminary clinical data from patients with advanced melanoma indicate that combining DC therapy with CTLA-4-targeting monoclonal antibodies enhances therapeutic efficacy compared to monotherapy." (PMID 40497988, 2025). "Agents such as nivolumab, ipilimumab, and pembrolizumab have improved survival in advanced melanoma, particularly in combination regimens targeting PD-1 and CTLA-4 pathways, though with notable toxicity profiles." (PMID 41375623, 2025). "ICIs that block cytotoxic T lymphocyte-associated protein 4 (CTLA-4) or programmed cell death 1 (PD-1) or its ligand PD-L1 are approved for the treatment of a variety of cancers, including melanoma, non-small cell lung carcinoma, and cervical cancer." (PMID 40806825, 2025). "In melanoma patients after anti-CTLA-4 treatment, peripheral CD4+T-cell clones proliferate and are enriched in corresponding tumors." (PMID 40226614, 2025). "BRAF/MEK inhibitors (BRAFi/MEKi) and PD-1 and CTLA-4 immune checkpoint inhibitors (ICI) have revolutionized malignant melanoma treatment and improved patients’ clinical outcome significantly." (PMID 40310541, 2025). "Both Concanamycin A (ConcA) and TAK-243 treatment rescued endogenous CTLA4 protein from degradation under Cycloheximide chase conditions in melanoma and lung cancer cells, whereas the proteasome inhibitor (Epo) was without effect." (PMID 39404738, 2025). "Accordingly, the epigenetic drugs induced type I interferon (IFN)-related genes, such as IFIs, IFNβ1, IRF7, OASL, and STAT1, in ovarian cancer cells and sensitized them to anti-CTLA4 immunotherapy in a melanoma mouse model." (PMID 40805133, 2025). "Additional research has indicated that, for melanoma patients receiving PD-1, CTLA-4, or combined ICIs, the administration of VD significantly decreases the likelihood of developing ICI-induced colitis." (PMID 40806182, 2025). "The use of antibodies against PD-1 and CTLA4 has been transformative in the management of many cancers, particularly melanoma." (PMID 40457060, 2025). "In cancer therapy, the combination of anti-CTLA4 and anti-PD-1 antibodies has demonstrated enhanced anti-tumor efficacy compared to monotherapy in various cancers, including melanoma and non-small-cell lung cancer." (PMID 40643506, 2025). "The combination of T-VEC and ipilimumab (monoclonal antibody to CTLA-4 for the treatment of advanced melanoma has shown signs of success." (PMID 40092697, 2025). "We consulted the cancer cell line encyclopedia (CCLE) database for cancer cell lines expressing CTLA4 and selected one melanoma (A2058) and one squamous lung carcinoma (NCI-H520) cell line for further investigation." (PMID 39404738, 2025). "The combination of anti-CTLA-4 monotherapy with an IDO1 inhibitor resulted in melanoma tumor regression and was dependent on the activity of CD8 + T-cells and IFN-γ." (PMID 40108693, 2025).
melanoma (continued). "Immune checkpoint inhibitors (ICI) targeting PD-1 and CTLA-4 have transformed the management of advanced melanoma and were chosen for this patient." (PMID 41384184, 2025). "A single patient with metastatic (stage IV) melanoma treated with combination ipilimumab (anti‐CTLA‐4) and nivolumab (anti‐PD‐1) had serial blood draws prior to and during the course of treatment." (PMID 40457714, 2025). "Over the past few years, immune checkpoint inhibitors (ICIs) targeting programmed cell death 1 (PD-1), its ligand 1 (PD-L1) and cytotoxic T-lymphocyte antigen-4 (CTLA-4) have radically changed the management of many types of solid tumors including melanoma." (PMID 40554927, 2025). "CTLA-4 and relative eosinophil count (REC): CTLA-4 is a negative regulator of T-cell activation targeted by ipilimumab in melanoma and other cancers." (PMID 40717879, 2025). "Immune checkpoint inhibitors (ICIs), such as anti-programmed cell death protein 1 (PD-1) and anti-cytotoxic T-lymphocyte associated protein 4 (CTLA-4), have transformed the management of stage III melanoma in the neoadjuvant setting." (PMID 41291768, 2025). "The combination of nivolumab (anti-PD-1) plus ipilimumab (anti-CTLA-4) has achieved a 10-year overall survival (OS) rate of 43% and a melanoma-specific survival (MSS) rate of 52% for patients with advanced melanoma." (PMID 41291768, 2025). "The development of immune checkpoint inhibitors such as anti-CTLA-4 and anti-PD-1 antibodies has significantly improved tumor regression and long-term cancer control in patients with melanoma." (PMID 38751816, 2024). "Among 27 patients treated with adoptive T-cell therapy (ACT) for stage IV melanoma after failing prior immunotherapies (i.e., anti-CTLA-4 and/or intravenous IL-2), higher predicted neoantigen and mutational loads were associated with clinical benefit." (PMID 39336897, 2024). "To date, there is strong evidence that CD8+ T cells confer a better prognosis in melanoma patients and that their expansion occurs after anti-CTLA-4 and anti-PD-1 monotherapy as well as anti-PD-1 plus anti-CTLA-4 combination treatment." (PMID 39273452, 2024). "In various cancers, including NSCLC and melanoma, immune checkpoint receptors such as PD-1 and CTLA4 are highly co-expressed on immune cells like exhausted CD8+ T cells." (PMID 38713378, 2024). "Another important connection is the increased presence of B. fragilis and Bifidobacterium species in the fecal samples of patients with melanoma who received CTLA4 blockade." (PMID 38617537, 2024). "We systematically compared different immunotherapies that lead to tumor rejection, including NeoAg cancer vaccines, anti-CTLA-4, anti-PD-1, and anti-CTLA-4 + anti-PD-1 ICT using mouse melanoma models expressing defined NeoAgs." (PMID 38187708, 2024). "Here the authors report genetic and immunological patterns of resistance in patients with melanoma after progression on anti-CTLA4 or anti-PD1 monotherapy." (PMID 38594286, 2024). "For this purpose, the peripheral blood mononuclear cells (PBMCs) from anti-CTLA4 treated (monotherapy) melanoma patients were assessed by flow cytometry." (PMID 39737964, 2024). "In one study, including 68 patients with advanced melanoma treated with anti-CTLA-4 or anti-PD-1, the median level of circulating DNT decreased, while CD4+ and NK cells increased in patients who responded to treatment compared to those who did not." (PMID 39273452, 2024). "In immunotherapy, the combination of anti‐CTLA‐4 antibody and anti‐PD‐1 antibodies has been approved for the treatment of advanced melanoma, yielding favorable outcomes." (PMID 39399646, 2024). "These inhibitors, particularly anti-CTLA-4 and anti-PD-1 inhibitors, have transformed the management of various cancers, notably advanced melanoma." (PMID 38891988, 2024). "The anti-CTLA-4 antibody ipilimumab and the anti-PD-1 antibodies nivolumab and pembrolizumab are currently the approved immune checkpoint inhibitor drugs for melanoma treatment." (PMID 38183141, 2024).
melanoma (continued). "The use of anti-PD-1 therapies in cSCC and HNSCC, and anti-CTLA-4 alone or in combination with anti-PD-1 in melanoma have represented a major advance in cancer treatment." (PMID 38914547, 2024). "Another group conducted single methylation analysis of the CTLA-4 promoter using samples from 50 patients with metastasized malignant melanoma who were treated with anti-PD-1/CTLA-4 therapy." (PMID 39000359, 2024). "In melanoma, Wnt-β catenin signaling impedes T-cell infiltration and fosters resistance to CTLA-4/PD-1 blockade." (PMID 38785789, 2024). "Ipilimumab, an inhibitor of CTLA-4, was approved for the treatment of advanced or unresectable melanoma." (PMID 39286684, 2024). "On the other hand, increased IL-17 signaling and serum levels of IL-17 correlated positively with positive outcome of dual CTLA-4 and PD-1 checkpoint inhibition in melanoma and improved OS of the patients." (PMID 38927967, 2024). "Immunotherapies targeting the combined inhibition of CTLA-4 and PD-1 have demonstrated efficacy in melanoma, renal cell carcinoma, and non-small cell lung cancer." (PMID 38294629, 2024). "It appears that MHC-I expression elicits a response against CTLA-4 melanoma, whereas an anti-PD-1 response requires a pre-existing IFN-γ-mediated immune activation." (PMID 37877810, 2024). "Several checkpoint inhibitors, including the anti-CTLA-4 and the anti-PD-1 monoclonal antibodies, are approved for the treatment of advanced melanoma." (PMID 39435293, 2024). "The H11-VHHkappa conjugate showed superior efficacy in the MC38 model compared to the anti-CTLA-4 mAb 9H10 and showed similar efficacy in the B16-F10 melanoma model." (PMID 39149504, 2024). "Together, these results substantiate the potential use of CTLA-4 ICIs as the standard of care in cases of advanced melanoma upon future treatment optimization." (PMID 39682188, 2024). "MAP prediction confirmed the effect of selected markers, especially IL6 and CTLA4, on the activation of melanoma disease." (PMID 39336572, 2024). "CheckMate-067 trial: This trial assessed the combination of nivolumab (anti-PD-1) and ipilimumab (anti-CTLA-4) in patients with advanced melanoma." (PMID 39518676, 2024). "The success of immune checkpoint inhibitors, anti-CTLA-4 in treating melanoma and anti-PD-1/PD-L1 in multiple types of cancer, has emphasized the potential of immunotherapy as a promising treatment option for patients with hematologic malignancies." (PMID 39766080, 2024). "A retrospective single-center analysis of melanoma patients demonstrated that 11 out of 134 male patients (8%) developed hypophysitis following anti-CTLA-4 (ipilimumab) treatment within four months after the first dose." (PMID 38539511, 2024). "The authors found that a liposomal formulation of anti‐CTLA‐4 increased survival and reduced tumor size in B16 melanoma mouse models compared with free anti‐CTLA‐4." (PMID 38435821, 2024). "In 2011, the FDA approved the anti-CTLA-4 antibody ipilimumab for melanoma treatment, marking the beginning of a new era in clinical therapy." (PMID 39839672, 2024). "Here, we collect biopsies from a cohort of 44 patients with melanoma after progression on anti-CTLA4 or anti-PD1 monotherapy." (PMID 38594286, 2024). "This human IgG1 monoclonal antibody is utilized in the treatment of melanoma, kidney, and esophageal cancers by inhibiting CTLA4, a protein known to suppress the immune system." (PMID 38931856, 2024). "Targeting CTLA4 with “immune checkpoint inhibitors”, such as ipilimumab, an antibody acting on human CTLA4 protein, has emerged as an exciting approach in melanoma treatment, particularly for progressing unresectable cutaneous melanoma in adult humans." (PMID 39336572, 2024). "For example, bicarbonate improved response to several immunotherapies (anti-PD-1 and anti-CTLA4 mAbs and adoptive cell therapy) in melanoma xenograft models by increasing TME pH and counteracting immunosuppressive effects mediated by the acidic TME pH." (PMID 39065587, 2024).